ASB18 (ankyrin repeat and SOCS box containing 18)
Description:
May be a substrate-recognition component of a SCF-like ECS (Elongin-Cullin-SOCS-box protein) E3 ubiquitin-protein ligase complex which mediates the ubiquitination and subsequent proteasomal degradation of target proteins.
Synonyms: ASB-18
Tractability: No criterion of Open Targets' tractability assessment is met for any kind of drug.
Gene: Protein-coding gene on chromosome 2 (236,193,459 to 236,264,409, reverse strand). Ensembl gene ENSG00000182177.
Subcellular location (Human Protein Atlas): Mitochondria; Nucleoli
Pathways (Reactome):
Immune System: Antigen processing: Ubiquitination & Proteasome degradation
Metabolism of proteins: Neddylation
Gene Ontology:
Biological process: intracellular signal transduction; protein ubiquitination
Cellular component: cytosol
Genetic constraint (gnomAD): Loss-of-function variants: 31 observed, 23.41 expected, observed/expected ratio (o/e) 1.32, 90% interval 0.99 to 1.76. The synonymous counts are far from expectation, so gnomAD's model fits this gene poorly and the ratio says little. Missense variants: 680 observed, 483.61 expected, observed/expected ratio (o/e) 1.41, 90% interval 1.32 to 1.5. Synonymous variants: 288 observed, 216.21 expected, observed/expected ratio (o/e) 1.33, 90% interval 1.21 to 1.47.
Homologues: Orthologues: chimpanzee ASB18 (99% identical), pig ASB18 (84% identical), mouse Asb18 (79% identical), rat Asb18 (79% identical), guinea pig ASB18 (76% identical), dog ASB18 (73% identical), rabbit ASB18 (68% identical), Drosophila melanogaster CG9121 (25% identical), Drosophila melanogaster CG13933 (22% identical). Paralogues in human: ASB10 (41% identical), ASB16 (36% identical), ASB4 (32% identical), ASB14 (23% identical), ASB15 (22% identical), ASB3 (20% identical), MPHOSPH8 (20% identical).
Diseases named in the same sentence as ASB18 in open-access papers:
ASB18 is named in the same sentence as 2 diseases in open-access papers, as found by Europe PMC text mining. Sharing a sentence is not in itself a finding about the gene and the disease.
ASB18 shares sentences with these, for which no sentence is quoted: lung carcinoma (1 paper); lung squamous cell carcinoma (1).